FKBP4 (FKBP prolyl isomerase 4)
Diseases named in the same sentence as FKBP4 in open-access papers (continued):
Sharing a sentence is not in itself a finding about the gene and the disease.
hypospadias (4 papers, 2007 to 2025). Hypospadias is the displacement of the urethral meatus on the ventrum of the penis. "Studies of such patients described mutations in other genes crucial for sexual development, such as the hypospadias-associated MAMLD1 gene or the FKBP4 gene, encoding a regulator of the AR signaling pathway." (PMID 40247401, 2025). "Here, we report for the first time a potentially causative FKBP4 gene mutation in a patient manifesting PAIS with hypospadias." (PMID 33182400, 2020). "Based on the 52KO mouse phenotype, mutations in FKBP4 may cause hypospadias in humans." (PMID 17343741, 2007). "In this report we examined the sequence and the expression of the FKBP4 gene in the skin of boys with different severities of hypospadias, and controls." (PMID 17343741, 2007). "Previously, a search for a FKBP4 gene mutation in a group of patients with hypospadias was described but no variant associated with that condition was found." (PMID 33182400, 2020). "The present report indicates that alterations in the sequence and in the expression of the FKBP4 gene are not a common cause of non-syndromic hypospadias." (PMID 17343741, 2007). "Despite the high homology (89%) between human and mice FKBP52 proteins, with conserved functional domains, our results suggest that alterations on the human FKBP4 coding sequence and expression are not a common cause for non-syndromic hypospadias." (PMID 17343741, 2007). "No sequence variants in the FKBP4 gene have implicated in hypospadias in our study." (PMID 17343741, 2007). "However, this dominant mode of inheritance is not in line with the mouse model, in which heterozygous Fkbp4 mutant males did not display hypospadias and were fertile, in contrast to homozygous Fkbp4 mutant animals displaying a phenotype corresponding to PAIS." (PMID 33182400, 2020). "FKBP52 is likely to play a role in growth and development of the male genitalia, since it is expressed in the genital skin of prepubertal boys; however alterations in the sequence and in the expression of the FKBP4 gene are not a common cause of non-syndromic hypospadias." (PMID 17343741, 2007).
androgen insensitivity syndrome (3 papers, 2015 to 2025). Androgen insensitivity syndrome (AIS) is a disorder of sex development (DSD) characterized by the presence of female external genitalia, ambiguous genitalia or variable defects in virilization in a 46,XY individual with absent or partial responsiveness to age-appropriate levels of androgens. "rs56196860 is a missense variant in FKBP4, which is a reported candidate gene for androgen insensitivity syndrome." (PMID 41131989, 2025).
bladder cancer (3 papers, 2020 to 2022). "Five genes are amplified in > 5% of the corresponding TCGA cohorts: E2F3 (cytoband 6p22.3, 15.7% of bladder cancer), TFRC (3q29, 13.0% of head and neck cancers), MFSD3 (8q24.3, 7.9% of head and neck cancers, FKBP4 (12p13.33, 6.8% of ovarian carcinoma) and FBXL20 (17q12, 6.4% of gastric cancer)." (PMID 34313788, 2021).
colon cancer (3 papers, 2020 to 2025). "Here, we report a functional pool of FKBP4, a co-chaperone protein, in the mitochondrial intermembrane space (IMS) of colon cancer cells." (PMID 35981890, 2022). "FKBP4 controls mitochondrial respiration via modulating COA6-mediated biogenesis and activity of mitochondrial complex IV, thereby regulating 5-fluorouracil sensitivity in colon cancer." (PMID 35981890, 2022).
cervical carcinoma (2 papers, 2021 to 2023). A carcinoma arising from either the exocervical squamous epithelium or the endocervical glandular epithelium. "These genes were uploaded to the GEPIA database, which showed that in cervical cancer and paracancerous tissues, the expression levels of seven genes, CD47, FKBP4, IRF-1, LDHA, PDIA3, TFRC, and SLC16A1, were significantly higher in cancer tissues (p < 0.05) than in healthy tissues." (PMID 36894874, 2023).
lung adenocarcinoma (2 papers, 2020 to 2021). A carcinoma that arises from the lung and is characterized by the presence of malignant glandular epithelial cells. "However, there is still no research to address the role of FKBP4 on lung adenocarcinoma (LUAD) progression." (PMID 34112753, 2021).
melanoma (2 papers, 2020 to 2022). A malignant, usually aggressive tumor composed of atypical, neoplastic melanocytes. "The gray scale quantification of these images showed that the expression of FKBP4 and RCC1 was significantly upregulated in melanoma, while the expression of PRADC1 was slightly upregulated, and the expression of GBP1 was downregulated (P < 0.05)." (PMID 33194692, 2020). "These 13 mRNAs were further analyzed by multivariate COX proportional hazard regression analysis, and finally, four hub mRNAs that could be used to predict melanoma prognosis were selected: PRADC1, FKBP4, RCC1, and GBP1." (PMID 33194692, 2020).
Obesity (2 papers, 2020 to 2021). Accumulation of substantial excess body fat. "Located within the same 12p13.33 region, the genes DCP1B, TSPAN9, and FKBP4 also overlapped between hypomania and schizophrenia, and have previously been associated with a range of physical health phenotypes including obesity and waist–hip ratio." (PMID 32152294, 2020).
polycystic ovary syndrome (2 papers, 2021 to 2023). A disorder that manifests as multiple cysts on the ovaries. "The FKBP4 SNP rs4409904 was associated with lower odds of polycystic ovary syndrome." (PMID 33936178, 2021).
triple-negative breast carcinoma (2 papers, 2019 to 2020). An invasive breast carcinoma which is negative for expression of estrogen receptor (ER), progesterone receptor (PR), and human epidermal growth factor receptor 2 (HER2). "In tumors, it has been demonstrated that FKBP4 plays a role in triple-negative breast cancer and castration-resistant prostate cancer; however, the role of FKBP4 in other tumors has not been reported." (PMID 33354489, 2020). "It was illustrated that FKBP4 can promote the growth of triple-negative breast cancer cell models and xenograft tumor models." (PMID 33354489, 2020). "In this study, we inhibited FKBP4 in the highly aggressive, poorly differentiated and triple negative breast cancer cell line MDA-MB-231." (PMID 31660083, 2019). "Our results suggest that inhibition of FKBP4 induces a cell cycle arrest in triple-negative breast cancer cells through down-regulation of the PI3K/Akt signaling activity, resulting in Cyclin D1 downregulation." (PMID 31660083, 2019). "In summary, our data suggest that FKBP4 significantly potentiates the Akt signaling in triple-negative breast cancer." (PMID 31660083, 2019). "Furthermore, FKBP4 depletion specifically reduces cell growth and proliferation of triple negative breast cancer cell model and xenograft tumor model." (PMID 31660083, 2019).
Autoimmunity (1 paper, 2021). The occurrence of an immune reaction against the organism's own cells or tissues. "Thus, FKBP4 and NR3C1 could serve as notable therapeutic molecules against NRF2-dependent tumorigenesis, autoinflammation, and autoimmunity in the future." (PMID 35087512, 2021).
breast tumor (1 paper, 2019). "The rate of moderate to high FKBP4 expression was significantly higher in grade 2 (82.8%, 29/35) and grade 3 (85.7%, 30/35) than in grade 1 (46.7%, 7/15) breast tumors (P<0.01)." (PMID 31660083, 2019). "To test FKBP4 differential expression across breast tissues, we performed IHC on breast tumors and CIS samples." (PMID 31660083, 2019). "In the ER/PR-negative breast tumor data set (n=246), patients with high FKBP4 expression exhibited a shorter and significant RFS interval (Log-rank, P=0.026)." (PMID 31660083, 2019).
ductal carcinoma (1 paper, 2020). "FKBP4 is found to be over-expressed in ductal carcinoma and under-expressed in lobular carcinoma by expression profiling." (PMID 32139710, 2020).
large cell lung cancer (1 paper, 2020). "First, the Oncomine database was used to analyze the expression of FKBP4, and it was found that the expression of FKBP4 was upregulated both in large cell lung cancer and in squamous cell lung cancer compared with that in normal tissue." (PMID 33354489, 2020).
liver cancer (1 paper, 2024). An epithelial or non-epithelial malignant neoplasm that arises from the liver. "In prostate biopsy tissues 63 and liver cancer tissues 64 similar observations were made, suggesting that FKBP4 may be a potential biomarker for tumours." (PMID 38577594, 2024).
lymph node metastasis (1 paper, 2020). "In this study, it is also found that the expression of FKBP4 is closely related to the tumor size and lymph node metastasis of NSCLC, and its high expression suggests a poor prognosis for patients." (PMID 33354489, 2020). "FKBP4 expression is closely related to tumor size and lymph node metastasis." (PMID 33354489, 2020).
myeloma (1 paper, 2023). "Other FKBPs with relevant affinities to FK506 are FKBP13 (FKBP2) (Ki = 302 nM), FKBP51 (FKBP5) (Ki = 406 nM) and FKBP52 (FKBP4) (Ki = 56 nM), all of which are expressed in myeloma cell lines." (PMID 36717825, 2023).
oral cancer (1 paper, 2021). "FKBP4 was significant with a high fold change in oral cancer." (PMID 33936178, 2021).
oral squamous cell carcinomas (1 paper, 2020). "By means of proteomics- and microarray-based investigations, FKBP4 was identified as one of the upregulated (marker) proteins in neoplastic SCs from childhood germ cell tumors, mammosphere-derived breast CSCs, and oral squamous cell carcinomas." (PMID 32268506, 2020).
prostate tumor (1 paper, 2017). "Therefore, the intricate role of FKBP4 in regulating prostate growth may be anticipated because its increase at both the transcriptional and translational levels have been observed in prostate tumor tissues compared to BPH tissues." (PMID 28852180, 2017).
systemic lupus erythematosus (1 paper, 2021). An autoimmune multi-organ disease typically associated with vasculopathy and autoantibody production. "The rs12582595 of FKBP4 was correlated with general health improvement in systemic lupus erythematosus patients." (PMID 33936178, 2021).
type 2 diabetes (1 paper, 2022). "However, experimental studies are required to reproduce these molecular consequences of HSF1 deficiency and to draw definitive conclusions about the causal relationship between the HSF1 gene, molecular chaperones HSP90B1, HSPA5, and FKBP4, and impaired proinsulin folding in type 2 diabetes." (PMID 36431071, 2022).
virus) infection (1 paper, 2025). "For the last protein peptidyl-prolyl cis-trans isomerase (FKBP4) no reports were found of this proteins involvement in DENV (or other virus) infection, although this protein has been linked to glycolysis, which is known to be altered in DENV infected liver cells." (PMID 40748977, 2025).
cancer (33 papers, 2012 to 2025). A tumor composed of atypical neoplastic, often pleomorphic cells that invade other tissues. "High expression of FKBP4 is associated with the malignancy and progression of several types of human cancer." (PMID 35981890, 2022). "The key node identified for UCEC was Cg18776056, located on the gene FKBP4, which is a progestin receptor cochaperone protein associated with cancer malignancy." (PMID 36676027, 2022). "Acting as a scaffold, FKBP4 promotes interactions among key components of multiple cancer-promoting signaling pathways." (PMID 39050579, 2024). "FKBP4 is known to regulate nuclear translocation and/or transcriptional activity of several cancer-related transcription factors and thus contributes to malignancy and progression of several types of human cancer." (PMID 35981890, 2022). "FKBP4 acts as a scaffold protein to facilitate the interactions between key components of several cancer-promoting signaling pathways." (PMID 35981890, 2022). "In general, the expression of FKBP4 is increased in tumor tissues, and overexpression FKBP4 indicates a poor prognosis for cancer patients." (PMID 33936178, 2021). "Our previous work found that FKBP4 interacted with non-coding RNAs and mRNAs during the occurrence and development of BC, thus playing a role in promoting cancer." (PMID 35087512, 2021). "Due to the critical involvement of NF-κB signaling in multiple cancers, we assessed the effect of FKBP4 on malignant behavior of LUAD cells." (PMID 34112753, 2021). "A contribution of FKBP4 to cancer stemness manifestations, such as self-renewal, spheroid formation, and chemoresistance, has been reported as well." (PMID 32268506, 2020). "Our data showed that inhibition of FKBP4 altered cancer cell growth in vitro by inducing a G1 phase arrest." (PMID 31660083, 2019). "To gain mechanistic insight on the role of FKBP4 in this cancer subtype, we used mass spectrometry to characterize the in vivo proximal interactome of FKBP4 and demonstrated that FKBP4 is a novel PI3K/PDK1/mTORC2 proximal interacting protein." (PMID 31660083, 2019). "Immunohistochemical screening of BPH and cancer samples in patients validated over expression of the FKBP4 gene at the protein level." (PMID 28852180, 2017). "FKBP4 is a co-chaperone of Hsp90 and exhibits increased expression in multiple cancer types." (PMID 41203126, 2025). "CCT1, CCT5, and FKBP4 showed significantly lower expression in the cancer patients compared to the healthy volunteers, whereas HSPA9 and TRAP1 showed a significantly higher expression in patients with cancer compared to the control group for the most cancer types." (PMID 34692733, 2021). "In other non-cancer diseases, the expression of FKBP4 shows different trends in different diseases." (PMID 33936178, 2021). "Among these genes, FKBP4 showed ~5-fold up regulation in cancer tissues." (PMID 28852180, 2017). "In the present study, using Stitch EMBL, the interaction network analysis revealed that a coordination of candidate proteins (FKBP4, ESRRA, IGSF10 and ABCB5) was involved in KEGG pathways of many cancers." (PMID 36517562, 2022). "These genes are related to the immune system and tumors: GNG7 is related to PI3K-Akt and Chemokine, FKBP4 is related to Estrogen, and IGF2BP1 is related to miRNA in the cancer pathway, and CD40LG is related to the NF-kappa B and T cell receptors." (PMID 36249053, 2022). "In this study, FKBP4, ADCY9, and KRAS were differentially expressed in cancer tissues and adjacent normal tissues of LUAD and were related to the prognosis of LUAD." (PMID 33936178, 2021). "In our study, the expression of FKBP4 was up-regulated in LUAD, and patients with high FKBP4 expression had a relatively poor prognosis, which was the first report in LUAD and was consistent with the expression changes in other cancers." (PMID 33936178, 2021).
cancer (continued). "To explore the potential role of FKBP4 in LUAD progression, we analyzed the RNA-seq data (FPKM values) from The Cancer Genome Atlas (TCGA) database." (PMID 34112753, 2021). "The FK506-binding protein 4 (FKBP4, also known as FKBP52) has been reported to possess multiple functions in various kinds of cancers based on its interaction with different cellular targets." (PMID 32194784, 2020). "Although FKBP4 has been shown to reside in both the cytoplasm and nucleus in various cell types, the subcellular compartmentalization of FKBP4 and its role in cancer cells has not yet been addressed." (PMID 35981890, 2022). "Accordantly, FKBP5 that acts antagonistically to the function of FKBP4 was found to confer chemosensitization via negatively regulating AKT in several types of cancer cells." (PMID 35981890, 2022). "Based on the microarray data, our results confirmed that relative expression of FKBP4, c-myc and FGF8 were significantly higher in both low (Gleason score = 6) and high grades (Gleason score > 6) of cancer as compared to that of the mean BPH samples in a larger cohort." (PMID 28852180, 2017). "The inhibition of FKBP4 could reduce the expression of SSEA-4, leading to suppression of cancer malignant processes." (PMID 25006670, 2014). "Moreover, among the enriched genes in the group of cancer areas in the dHGP, we detected many genes known to enhance inflammatory reactions in cancer by promoting the NFκB pathway (IKBKB, FKBP4), activating lymphocytes (TNFSF9, HLA-F) or recruiting neutrophils (DPEP1)." (PMID 36691028, 2023).
tumor (21 papers, 2012 to 2025). "The univariate Cox model revealed that FKBP4 expression, primary tumor size, and clinical TNM stage were significantly associated with a shorter OS in LUAD patients." (PMID 34112753, 2021). "Moreover, we found that the FKBP4 expression levels (best cut-off value = 10.8319) were notably associated with gender, tumor size, and clinical TNM stage according to TCGA database." (PMID 34112753, 2021). "FKBP4 functions as an HSP90-associated co-chaperone and is a tumor-specific antigen to trigger immune responses." (PMID 39453509, 2024). "Identification of FKBP4/NR3C1/NRF2 axis would provide insights for novel anti-tumor strategy against BC among tumor microenvironment." (PMID 35087512, 2021). "Identification of FKBP4/NR3C1 axis as the novel NRF2 regulator would provide in-depth insights for immunological anti-tumor strategy to overcome BC." (PMID 35087512, 2021). "The results of subcutaneous tumor formation experiments in nude mice demonstrated that after silencing the FKBP4 gene, the tumor growth rate was significantly lower than that of the control group, indicating that tumor growth was inhibited." (PMID 33354489, 2020). "After that, tumor xenografts were used to explore the effect of FKBP4 on NSCLC tumor growth in vivo, and the phosphorylation of Akt and mTOR was measured by western blot." (PMID 33354489, 2020). "It was found that the expression of FKBP4 in tumor tissues was significantly higher than that in normal lung tissues." (PMID 33354489, 2020). "The subcutaneous tumor size reached 884 mm3 51 days post-graft in the control group, while the FKBP4 shRNA CDX tumor grew much slower, reaching 399 mm3 at day 51 (P<0.01)." (PMID 31660083, 2019). "We confirmed this effect on cell proliferation in a CDX tumor model in vivo, where the down-regulation of FKBP4 significantly impaired tumor growth." (PMID 31660083, 2019). "In this study, we showed that naringenin, a flavonoid shown to have anti-tumor effects in various carcinomas in other studies, suppressed both autophagy and proliferation via new-found FKBP4/NR3C1/NRF2 signaling pathway in luminal A and basal-like subtype of BC cells." (PMID 35087512, 2021). "Overexpression of FKBP4 could thus contribute to tumorigenesis by increasing proliferation and tumor growth." (PMID 31660083, 2019). "Additionally, naringenin could promote differentiation and maturation of DC among tumor microenvironment through regulating FKBP4/NR3C1/NRF2 signaling pathway." (PMID 35087512, 2021). "The results showed that FKBP4 and LOXL2 expression was significantly upregulated in the tumour cell lines." (PMID 38577594, 2024). "To investigate the role of CBPRS in the tumour microenvironment (TME) at the single-cell transcriptome level, we analysed the expression patterns of SOD1, MUC2, FKBP4, LOXL2, GPC1 and SNAI3 in different cell types." (PMID 38577594, 2024). "FKBP4, TK1, HERPUD1, and CLEC3B levels were measured and verified in clinical samples (tumor tissues)." (PMID 37341998, 2023). "GEO datasets validated that the 6 genes (SHC1, FKBP4, NRAS, PRKCD, KRAS, ADCY9) had different expression between tumor tissues and adjacent normal tissues in LUAD, and 3 genes (FKBP4, KRAS, ADCY9) were related to the prognosis of LUAD." (PMID 33936178, 2021). "For example, many genes involved in the modulation of the androgen receptor function were inhibited in the LNCaP xenograft tumor, including Hsp90AA2P, FLNA, and FKBP4." (PMID 33808801, 2021). "Among them, SHC1, FKBP4, NRAS, KRAS had higher expression, and PRKCD, ADCY9 had lower expression in LUAD tumor tissues compared with normal tissue." (PMID 33936178, 2021). "FKBP4 was highly expressed in NSCLC tissues and cells, and its expression was closely related to NSCLC tumor size, lymph node metastasis, and patient prognosis." (PMID 33354489, 2020).